TYR (tyrosinase)
Diseases named in the same sentence as TYR in open-access papers (continued):
Sharing a sentence is not in itself a finding about the gene and the disease.
melanoma (continued). "In our model, melanoma spheroids express HMB-45-reactive antigen, MART1/Melan A and/or Tyrosinase melanoma markers." (PMID 21526207, 2011). "Melanoma lines Malme-3M, mel526, and MeWo are HLA-A*0201-positive and express MAAs gp100, MART-1, and tyrosinase." (PMID 21794122, 2011). "Autoantibodies recognizing tyrosinase, TRP-1, and TRP-2, have been detected in the sera of melanoma patients and vitiligo patients." (PMID 21911918, 2011). "For instance, artificial promoters based on the elements of the promoters of the human tyrosinase and α-fetoprotein (AFP1) genes possessing strong and specific expression in melanoma cell lines were constructed." (PMID 22649681, 2011). "Similar to their adherent counterparts, both Mela1 and SLM8 (data not shown) spheroid cells stain positively for at least one of the frequently tested melanoma markers HMB-45, MART1/Melan A and/or tyrosinase." (PMID 21526207, 2011). "Among 142 upregulated genes in melanoma, many are known to be expressed specifically in melanocytes, including KIT, Melan-A, TYR, TRPM1, EDNRB, DCT, SOX10 and SILV." (PMID 21294715, 2011). "Since this seminal work, studies have turned largely to inducing CD8 T cell responses, and several MHC I-restricted epitopes from gp100, TRP-2, tyrosinase, and TRP-1 have since been employed as targets of melanoma vaccines and cellular therapies." (PMID 21911918, 2011). "Such high responses were reproduced with cells from 14–20 healthy donors and with various melanoma tumor-derived antigens such as MelA, GP100, TYR, MAGE-3 as well as virus-derived antigens." (PMID 20454561, 2010). "Several melanoma markers (e.g. gp100, MART-1 and tyrosinase) have been detected and proposed for immunotherapy approaches." (PMID 20479946, 2010). "In melanoma cells, TGF-beta has been shown to significantly inhibit melanin synthesis by increasing the rate of degradation of tyrosinase, a rate-limiting enzyme in the melanogenesis pathway." (PMID 20370932, 2010). "Immunostaining on zebrafish melanoma cryostat sections including Tyrosinase, Melan-a, s100 and HMB45, revealed elevated expression of all these melanoma markers showing that these tumors are immunologically similar to human melanoma." (PMID 21170325, 2010). "Western blotting data indicated that the antimelanogenic activity of treatment with combination of Tau and AZ is probably due to suppression of tyrosinase, TRP1, TRP2 and MITF and increase of ERK activation in B16F10 mouse melanoma cells." (PMID 20804622, 2010). "While routine blood testing is not cost effective for Stage I–III melanoma, newer serum markers for melanoma have been proposed, including melanoma inhibitory activity (MIA), tyrosinase, 5-S-cysteinyldopa and serum protein S-100B." (PMID 24281112, 2010). "Due to the potent tyrosinase inhibitory activity, it is reasoned that HNB suppressed cellular tyrosinase activity and total melanin content to 27% and 35%, respectively, in melanoma cells at 100 μM concentration, where cells maintained 87% viability." (PMID 19582213, 2009). "In murine melanoma cells, TGF-β decreases pigmentation by decreasing the stability of tyrosinase mRNA and protein, as well as decreasing the level and the activity of MITF." (PMID 20130821, 2009). "T cell repopulation coincided with the de novo appearance of melanoma antigen-specific CD8+ T cells in several patients as determined by flow cytometry using tetrameric MART-1, tyrosinase and gp100 peptide/MHC conjugates." (PMID 18334033, 2008). "Tyrosinase protein expression was detected in untreated DM6 and DM93 melanoma lines, with DM6 expressing higher amounts of tyrosinase than DM93." (PMID 19055839, 2008). "Seven patients expressed the HLA-A2*0201 class I MHC necessary for tetramer-based measurement of CD8+ T lymphocytes specific for the melanoma antigens, MART1, tyrosinase and gp100." (PMID 18334033, 2008).
melanoma (continued). "Typically melanoma is reactive for vimentin, S-100 protein, HMB-45, melan -A, tyrosinase, and microphthalmia transcription factor." (PMID 17910749, 2007). "These include the cancer testis antigens exemplified by the MAGE family as well as differentiation antigens such as tyrosinase and melan-A/MART-1 that are expressed by normal melanocytes as well as melanoma cells." (PMID 16819544, 2006). "Tyrosinase (TYR), an enzyme that is involved in the melanin biosynthesis pathway, is the marker most frequently used to detect the presence of CMC in melanoma patients; however, its clinical usefulness is highly debated." (PMID 17107608, 2006). "Such an example is the utilisation of tyrosinase, an enzyme present only in melanocytes, for the detection of MRD in melanoma patients." (PMID 16495929, 2006). "The 'MCW Melanoma Cocktail' (a mixture of MART-1 {1:500}, Melan- A {1:100}, and Tyrosinase {1:50} monoclonal antibodies) demonstrated an excellent discriminatory immunostaining pattern." (PMID 16999866, 2006). "Several other studies have reported isolation of HLA class II-restricted melanoma-specific CD4+ CTLs, including clones recognising MAGE-3, NY-ESO1 and tyrosinase epitopes." (PMID 16819544, 2006). "These include TCR's specific for melanoma antigens MAGE-3, gp100, tyrosinase and CAMEL, the widely expressed oncoprotein MDM2, and the Epstein-Barr Virus protein LMP2 expressed by Hodgkin's lymphoma." (PMID 16174302, 2005). "In our previous study, the 'MCW Melanoma Cocktail'- a mixture of monoclonal antibodies- MART-1 {1:500}, Melan- A {1:100}, and Tyrosinase {1:50} demonstrated a highly discriminatory immunostaining pattern." (PMID 15500702, 2004). "The aim of this study is to define the relationship between the tyrosinase expression in the peripheral blood and the clinical course of the disease in stage III disease-free melanoma patients after radical lymph node dissection." (PMID 14562017, 2003). "We present a quality control study in which we analysed the reproducibility of detection of tyrosinase and MART-1 transcripts in 106 blood samples from 68 melanoma patients (mainly stages III and IV)." (PMID 10360670, 1999). "When applying real-time quantitative PCR for tyrosinase and MART-1, we found that a low amount of SK-MEL-28 cell equivalents was present in the blood of melanoma patients, with a higher number of equivalents in the group with a consistently positive result." (PMID 10360670, 1999). "LFWE also suppressed melanin biosynthesis in B16-F10 melanoma cells without toxicity up to 500 μg/mL and significantly inhibited the protein expression levels of tyrosinase, TRP-1, and TRP-2, which promote melanin production." (PMID 41947429, 2026). "Theophylline, a purine alkaloid and the main ingredient in tea plants, has been found to improve the protein expression levels of MITF, TYR, TRP‐1 and β‐catenin and promote the phosphorylation of ERK and GSK3β to increase melanin content in B16F10 murine melanoma cells." (PMID 40457938, 2025). "In a previous study, we, therefore, employed B16BL6 mouse melanoma cells, in which 4SCAP and MB exhibited tyrosinase-dependent cytotoxicity, whereas RD did not." (PMID 39858507, 2025). "FixVac encoded four non-mutated melanoma-associated antigens: NY-ESO-1, MAGE-A3, tyrosinase, and TPTE." (PMID 40725830, 2025). "Next, to determine whether CPEO affects tyrosinase activity and melanin synthesis in B16BL6 melanoma cells exposed to α-MSH induced in UVA-irradiated HaCaT cells, we collected conditioned medium from UVA (10 J/cm2)-treated HaCaT cells." (PMID 41304724, 2025). "Furthermore, α-MSH-induced melanogenesis in B16F10 melanoma cells was attenuated by BK-5 exosomes through the suppression of MITF expression and subsequent downregulation of key melanogenic enzymes, including tyrosinase, TRP-1, and TRP-2." (PMID 41407325, 2025).
melanoma (continued). "Unlike melanoma, many cancer cell lines do not overexpress tyrosinase, an enzyme needed to convert quercetin into its active form, o-quinone." (PMID 40867327, 2025). "With respect to the role of tyrosinase palmitoylation in melanogenesis, 2-BP (25 μM, 48 h) treatment in HM3KO human melanoma cells reduced its palmitoylation level but increased protein levels (implicating elevated protein stability), as determined by the acyl-RAC and 17-ODYA methods." (PMID 40004137, 2025). "The expression of tyrosinase is either maintained or lost after malignant transformation of melanocytes, leading to tyrosinase-positive and tyrosinase-negative melanoma metastasis." (PMID 41002986, 2025). "Besides, Tyrosinase and gp100 peptides fused with OVA BiP peptide and recombinant HSP70 protein have also demonstrated promising therapeutic potential in melanoma." (PMID 40297581, 2025). "This study demonstrated that fisetin, up to 60 μM, is non-toxic and significantly decreases tyrosinase activity and melanin content in human melanoma cells." (PMID 41373883, 2025). "Moreover, SPEF inhibited the expression levels of key melanogenic proteins such as tyrosinase, TRP-1, TRP-2, and MITF by downregulating the phosphorylation levels of CREB and PKA in α-MSH-stimulated melanoma cells." (PMID 40003988, 2025). "Although this is crucial for understanding the mechanism of inhibition, it does not fully address the potential downstream effects of tyrosinase inhibition on melanogenesis and melanoma cell behavior." (PMID 40332760, 2025). "□ Melanoma: Common markers include S-100 protein, SOX-10, Melan A, HMB45, tyrosinase, and MITF." (PMID 40308487, 2025). "In addition, Scutellaria baicalensis Georgi extract inhibited tyrosinase activity and melanin synthesis in B16F10 cells, and the extract of Angelica sinensis decreased melanogenesis in co‐culture system of human melanoma and keratinocytes cells." (PMID 41351313, 2025). "Analogs 1 and 3 have strong anti-melanogenic potency in B16F10 mammalian cells owing to their anti-tyrosinase activity without perceptible cytotoxicity in melanoma cells (B16F10) and the main epidermal cells (HaCaT)." (PMID 39942621, 2025). "Specifically, treatment with PMMEXOs in B16-F10 melanoma cells led to decreased expression of MITF, TYR, TRP-1 and TRP-2, suggesting that PMMEXOs suppress melanin synthesis through the suppression of MITF-mediated transcriptional activation of melanin biosynthetic enzymes." (PMID 40747328, 2025). "The anti-melanogenic effects of rifampicin were assessed in B16F10 melanoma cells, showing no cytotoxicity at concentrations up to 40 μM and a significant reduction in intracellular tyrosinase activity and melanin content." (PMID 40005210, 2025). "Protein expression levels of known melanoma markers, such as MITF, MLANA, PMEL, TYR, and SOX10, had the lowest expression in EC-Mit samples (ANOVA, FDR < 6 × 10−4) and had a significantly lower expression in the EC-like subtypes when compared to the Mit-like subtypes." (PMID 40075679, 2025). "It is also the first to identify TYR and MITF as key protein targets of salidroside in melanoma." (PMID 40708947, 2025). "In addition, fisetin significantly decreased mRNA levels and suppressed the expression of MITF, tyrosinase, TRP-1, TRP-2, and PMEL in both melanoma and α-MSH-stimulated melanoma cells." (PMID 41373883, 2025). "T cell responses against melanocyte-specific antigens such as melanosomal proteins involved in pigment synthesis (i.e., gp100, tyrosinase, MART-1/Melan-A, TRP1, and TRP2) correlate with tumor regressions and vitiligo in vivo in mice and patients with melanoma." (PMID 37891002, 2024). "Moreover, the expression of TYR, MITF, EDNRB, and TRP-1/2 was elevated again when rosiglitazone and GW acted together on melanoma cells, as PPAR-γ was activated." (PMID 38159176, 2024).
melanoma (continued). "In that case, APAP@PEG/HMnO2 is modified to be triggered by tyrosinase so that the non-toxic prodrug acetaminophen (APAP) can be precisely escorted to the position of malignant melanoma." (PMID 39128942, 2024). "Kinetic analysis has documented that paeonol can act as a non-competitive repressor of tyrosinase and inhibit melanin synthesis in a dose-dependent manner in human melanoma cells, which provides a rationale for paeonol treatment of hyperpigmentation." (PMID 39588155, 2024). "To this aim, we exposed LOX IMVI sensitive melanoma cells to increasing concentrations of a BRAFi for two months and at each step of drug increase we collected total RNAs from samples to evaluate the levels of mir-579-3p, MITF, TYR, and AXL by qRT-PCR." (PMID 38472212, 2024). "Moreover, both extracts demonstrated potential for inhibiting melanin production and intracellular tyrosinase activity in human melanoma cells by decreasing the expression of the transcription factor MITF and the pigmentary genes TYR, TRP-1, and DCT." (PMID 38999635, 2024). "Furthermore, DP inhibited tyrosinase activity and decreased melanin production in α-melanocyte stimulating hormone (α-MSH)-induced B16F10 melanoma cells in a dose-dependent manner." (PMID 39195491, 2024). "Moreover, treatment with C. boreale MAKINO EO (CB-EO) from the flower reduces melanogenesis through the downregulation of tyrosinase via the ERK and MAPK pathway in α-MSH-stimulated B16BL6 melanoma." (PMID 38791435, 2024). "Along with the results observed in B16 mouse melanoma cells, the relative gene expression levels of MITF, TYR, TRP-1, and DCT, after exposure to IBMX treatment, were significantly upregulated to 1.65 ± 0.12, 1.73 ± 0.15, 1.53 ± 0.12, and 1.67 ± 0.13, respectively, compared to the control group." (PMID 39684912, 2024). "Additionally, 2-phenyl-1,4-naphthoquinones were reported to suppress both tyrosinase activity and melanin production in B16F10 murine melanoma cells." (PMID 38814149, 2024). "To determine whether T. maritima extracts suppress melanin production by inhibiting tyrosinase activity, we conducted experiments using α-MSH-induced melanoma cells." (PMID 39728107, 2024). "Tyrosinase inhibitory activity (using L-DOPA as substrate), expressed as IC50, for p-substituted 1–3 thiosemicarbazones and anti-melanogenesis activity (on B16 melanoma cells), reported as IC50, expressed as a function of lipophilicity for 4–6 thiosemicarbazones." (PMID 39683787, 2024). "Tyrosinase was the only TAA expressed in a majority (56.0%, n = 14) of pediatric melanoma samples." (PMID 38890171, 2024). "In addition, the presence of IL-1β can upregulate the expression of TYR and TRP-1 in mouse melanomas." (PMID 39335872, 2024). "In this experiment, B16F10 melanoma cells were treated with α-MSH (200 nM) and T. himalayense extracts (25, 50, and 100 μg/ml) and subsequently cultured to investigate the effect of THWE and THEE on tyrosinase activity." (PMID 38480002, 2024). "Melanin levels are downregulated by treatment with OS-EO, OE-EO, or CRV without any alterations to tyrosinase activity in B16-F1 melanoma." (PMID 38791435, 2024). "We here demonstrate that tyrosinase (but not Tyrp-1) in B16 melanoma cells undergoes ubiquitination and subsequent degradation in lysosomes." (PMID 38392670, 2024). "In B16 melanoma cells, α-MSH activates tyrosinase and melanogenesis via adenyl cyclase activation." (PMID 38393043, 2024). "Statistical analysis was not performed for tyrosinase expression because this TAA was detected in all pediatric melanoma samples." (PMID 38890171, 2024). "Peel and pulp extracts were compared for their antiradical activity (using DPPH and ABTS radical scavenging assays), skin-lightening potential (tyrosinase inhibitory assay), sun protection factor (SPF), and cytotoxicity toward human fibroblast, keratinocyte, and melanoma cell lines." (PMID 38474645, 2024).
melanoma (continued). "Therefore, this study sought to investigate the effects of T. himalayense NIBRFG0000505337 on the expression of tyrosinase, TRP-1, TRP-2, and MITF in α-MSH-treated B16F10 melanoma cells." (PMID 38480002, 2024). "In addition, PTS showed a tyrosinase-dependent cytotoxicity against B16BL6 melanoma cells that was stronger than RES and also inhibited the formation of melanin in B16BL6 melanoma cells and in the culture medium." (PMID 39337478, 2024). "Consequently, we performed tyrosinase zymography, Western blotting, and quantitative RT-PCR analysis on D. pannonicus-treated B16F1 melanoma cells." (PMID 39768251, 2024). "The differential inhibition of this reaction by Zn (II) does not exclude the inactivating effect of this ion on melanoma tyrosinase." (PMID 36901791, 2023). "A-alum-1 decreased the slightly induced MITF mRNA and protein expression levels after 24 h of α-MSH treatment, suggesting that A-alum-1 decreases levels of tyrosinase mRNA and protein in the α-MSH-induced B16F1 melanoma cells via suppressing intracellular MITF mRNA and protein levels." (PMID 37834109, 2023). "We conclude that the tyrosinase-KO, melanin(–) tumors show no other significant differences to the progenitor B16 melanoma, neither at the morphological, cancer pathway or transcriptomics level." (PMID 37016073, 2023). "MNT-1 melanoma cells revealed a significant decrease in cAMP of 45% (MEL), 53% (AFMK), 62% (5-MT) and 49% (6(OH)MEL) according to our observation of decreased TYR activity and melanin synthesis." (PMID 37834395, 2023). "8-OHDe was shown to inhibit TYR activity in B16 melanoma cells with an IC50 of 6.17 μM and was not cytotoxic." (PMID 37570734, 2023). "Additionally, pinostrobin significantly decreased α-melanocyte-stimulating hormone (α-MSH)-induced extracellular and intracellular melanin production, as well as tyrosinase activity, in B16F10 melanoma cells." (PMID 36614262, 2023). "Furthermore, recent research has indicated that IL-1β partially mediates UVB-induced melanogenesis by upregulating the expression of TYR and TRP1 in melanoma B16 cells." (PMID 37781032, 2023). "Importantly, the pigmentation markers Tyrosinase and DCT were reduced, both at protein and mRNA level, in human melanoma cell lines Mel JuSo, IPC-298 and SK-MEL-3 following downregulation of TG2 by siRNA." (PMID 37898636, 2023). "In contrast, RF1 showed the best inhibition on cellular tyrosinase (18.26%) and melanin content (10.69%) in UV-induced melanoma cells at 70 μM without any cytotoxicity." (PMID 36834568, 2023). "In addition, Biomarkers such as S100 protein, micropthlamia transcription factor (MITF), tyrosinase and SOX10 are also widely used in the diagnosis of melanoma." (PMID 37427124, 2023). "However, human melanoma tumors are quite heterogeneous, with stem-like cell populations as well as more differentiated populations expressing MITF, TYR, and MELANA." (PMID 37270599, 2023). "Our results were comparable to other studies indicating the non-toxic effect and consistent anti-tyrosinase activities of KA and arbutin on melanoma cells." (PMID 36834568, 2023). "Tyrosinase CRISPR knock out in the B16 melanoma cell line eliminates melanin production, with the lack of pigment not affecting tumour engraftment or growth and allowing for 3D imaging after clearing by PACT." (PMID 37016073, 2023). "Compound 1 and products 2–5 were evaluated using mushroom tyrosinase activity assays with two substrates (L-tyrosine and L-DOPA), then cellular assays using B16F10 mouse melanoma cells, MNT-1 human melanoma cells, and physiological normal human melanocytes (HEMn-DP cells)." (PMID 37374155, 2023). "Unlike previous studies, pinostrobin effectively inhibits melanin biosynthesis in α-MSH-treated B16F10 melanoma cells and zebrafish larvae at 50 and 25 μM, respectively, which is relatively low compared with the IC50 (approximately 700 μM) of in vitro mushroom tyrosinase." (PMID 36614262, 2023).